BRAF (B-Raf proto-oncogene, serine/threonine kinase)
Diseases named in the same sentence as BRAF in open-access papers (continued):
Sharing a sentence is not in itself a finding about the gene and the disease.
metastatic melanoma (continued). "Four databases were systematically searched for randomized clinical studies that included patients with advanced/metastatic melanoma receiving chemotherapy, immune checkpoint inhibitors, BRAF/MEK inhibitor therapy, or combinations thereof." (PMID 39684531, 2024). "Before the Food and Drug Administration (FDA) approval of the BRAF inhibitor vemurafenib in 2011, limited treatment options were available for metastatic melanoma, and mortality rates were high." (PMID 39542696, 2024). "These clinical trials suggest that nivo/ipi should be administered before BRAF/MEKi in BRAFV600-mutant metastatic melanoma." (PMID 39337055, 2024). "Patients with BRAF and NF1 mutations were the only ones who had brain metastases when metastatic melanoma was diagnosed (12.9%)." (PMID 38339344, 2024). "Previous studies suggested that somatic BRAF and NRAS mutations in metastatic melanoma increase the risk for brain metastases." (PMID 38339344, 2024). "Clinical trial data suggest that first-line anti-PD-1 + anti-CTLA-4 combination therapy results in better survival rates in patients with BRAF V600 mutant metastatic melanoma than first-line BRAF + MEK inhibitor combination therapy." (PMID 39272837, 2024). "Despite the improved survival observed in patients with BRAF-mutant metastatic melanomas by the use of BRAF inhibitors, their efficacy is limited in individuals with thyroid cancer." (PMID 38795180, 2024). "Two cases of GA were reported in patients receiving vemurafenib, a BRAF inhibitor, for metastatic malignant melanoma." (PMID 39651032, 2024). "An ORR of 63–67%, mPFS of 9.3–14·9 m, and overall survival benefits have been demonstrated in randomized trials of targeted therapy with BRAF/MEK inhibitors in metastatic melanoma." (PMID 38339280, 2024). "Over recent years, different BRAF inhibitors have been approved by the FDA for the treatment of metastatic melanoma and have shown improved median PFS as a single agent." (PMID 39018564, 2024). "In conclusion, we reviewed metastatic melanoma’s genetic and biological properties, highlighting the significance of molecular mutations like NRAS, BRAF, NF1, and others in disease progression and treatment responses." (PMID 38534309, 2024). "CTC populations decreased in patients after receiving immunotherapy for BRAF, NRAS, and KIT mutant alleles in metastatic melanoma, highlighting the utility of monitoring CTC response to treatment to identify BRAF-mutant non-responders." (PMID 39156972, 2024). "The most common targeted therapy (TT) in the treatment of metastatic melanoma is BRAF and MEK inhibition." (PMID 39594689, 2024). "If metastatic tissue sampling is not feasible, analysis can be performed on primary tumor samples, as there is a high concordance rate of BRAF status between primary and metastatic melanoma lesions." (PMID 38541077, 2024). "Before the approval of the first BRAF inhibitor, chemotherapy was the standard of care for patients with advanced or metastatic melanoma." (PMID 39336897, 2024). "Mutations in PIK3CA p.E545K and amplification in ERBB2 were common in breast cancers, BRAF p.V600E in metastatic melanoma and IDH1 p.R132H in IDH-mutant gliomas." (PMID 39289779, 2024). "It was shown that BRAF inhibitors improve the overall survival of metastatic melanoma patients by blocking cell growth signals with low toxicity to the healthy tissues." (PMID 39459201, 2024). "Patients with metastatic melanoma and a mutation in the BRAF gene can be both treated with immunotherapy, including anti-CTLA4+anti-PD1 combination therapy or targeted therapy with BRAF and MEK inhibitors." (PMID 39469641, 2024). "Dabrafenib therapy for metastatic melanoma focuses on blocking growth-promoting signals produced by a hyperactive BRAF protein." (PMID 38254853, 2024).
metastatic melanoma (continued). "Five of the 12 patients, who received concurrent dabrafenib and trametinib as standard treatment for their V600 BRAF-mutant metastatic melanoma, experienced 59% of the low-grade AEs." (PMID 38754916, 2024). "Over the past 15 years, precision therapies targeting BRAF have been used to treat patients with metastatic melanomas." (PMID 39018217, 2024). "More robust efficacy analysis of patients with BMs has been conducted for BRAF-mutant metastatic melanoma treated with BRAF/MEK inhibitors." (PMID 38627602, 2024). "By elucidating the mechanisms underlying resistance development and identifying druggable targets, we hope to provide new therapeutic options that can improve patient outcomes and ultimately overcome resistance to BRAF inhibitors in metastatic melanoma." (PMID 39063187, 2024). "The SECOMBIT phase II trial explored the optimal sequential treatment for metastatic melanoma patients: BRAF/MEK inhibitors as the first line followed by immunotherapy, or immunotherapy as the first line followed by BRAF/MEK inhibitors." (PMID 39727691, 2024). "Knowledge about resistance mechanisms to BRAF inhibition results mainly from studies conducted in metastatic melanoma." (PMID 38177660, 2024). "Among several treatment options for BRAF-mutant metastatic melanoma, a combination of BRAF inhibitor, MEK inhibitor, and anti-PDL1 antibody seems to be a new emergent approach recently registered in the Russian Federation." (PMID 39469641, 2024). "Consistently, one study focusing on the sequence of ICI before and after neoadjuvant suggested that the ICI before neoadjuvant was efficacious in BRAF-wildtype metastatic melanoma." (PMID 38550601, 2024). "Dabrafenib is a BRAF V600 inhibitor approved for metastatic melanoma in 2013, after it was shown to significantly improve PFS over dacarbazine in patients with a BRAF V600 mutation and untreated metastatic disease." (PMID 39272885, 2024). "The main limitation of this study lies in its non-randomized design, precluding direct comparisons with immunotherapy and other BRAF / MEK inhibitors currently approved for the treatment of patients with metastatic melanoma." (PMID 38946469, 2024). "In a multicenter, retrospective case series investigation, encorafenib plus binimetinib combination treatment of 24 patients with BRAF-mutant metastatic melanoma BMs resulted in IC ORR of 33% and ORR of 21%101." (PMID 38627602, 2024). "This study provides real-world insights into the clinical outcomes and management of metastatic melanoma patients treated with ICIs and BRAF/MEKi in both the adjuvant and unresectable setting in a tertiary referral center in Switzerland." (PMID 38473216, 2024). "The field of targeted therapy has been testing various combinations to address drug resistance, and a great example is BRAF targeted therapy for patients with metastatic melanoma." (PMID 38686626, 2024). "BRAF kinase plays a key role in driving the proliferation of metastatic melanoma, a highly aggressive tumor with a generally poor prognosis affecting over half of the patients diagnosed with this condition." (PMID 39459201, 2024). "In our study, we found that elevated baseline serum S100B levels were associated with a higher risk of progression and death compared with normal baseline serum S100B levels in BRAF V600 mutant metastatic melanoma patients treated with BRAF + MEK inhibitors." (PMID 39272837, 2024). "Reactivation of ERK upstream or downstream of BRAF kinase constitutes the main secondary resistance mechanism to BRAF inhibition in metastatic melanoma." (PMID 38177660, 2024). "The combination of BRAF and MEK inhibitors (vemurafenib and cobimetinib) was approved in 2015 for treatment of patients with unresectable or metastatic melanoma who harbor a BRAF V600E or V600K mutation." (PMID 38474231, 2024). "According to literature data, the neutrophil-to-lymphocyte ratio can be an independent prognostic factor in metastatic melanoma treated with BRAF + MEK inhibitor." (PMID 39272837, 2024).
metastatic melanoma (continued). "In a previous meta-analysis, a clinically significant discrepancy in BRAF status was observed between metastatic and primary metastatic melanoma lesions." (PMID 39336897, 2024). "The development of mutant-selective BRAF inhibitors (BRAFi), like vemurafenib, has been efficacious in patients with metastatic melanoma, but the response rate is low for mutant BRAF PTC patients." (PMID 38622136, 2024). "Targeted therapies with BRAF- and MEK-inhibitors have significantly improved outcomes for patients with metastatic melanoma, but they come with a risk of heart-related side effects." (PMID 39272803, 2024). "Other studies have explored new drug combinations for the treatment of patients with BRAF-mutant unresectable or metastatic melanomas." (PMID 39727691, 2024). "In metastatic melanoma, eIF4F has been identified as a driver of resistance to therapies targeting BRAF and MEK, and simultaneous inhibition of BRAF and eIF4F activity synergized in killing tumor cells." (PMID 39436655, 2024). "When analyzing differential expression using GEPIA2, we have found a significantly higher expression for LOXL3 and NES in cutaneous metastatic melanoma, both in BRAF+ and BRAF– tumors, compared to normal skin samples." (PMID 39273022, 2024). "Trametinib is a monotherapy-approved MEK1/MEK2 inhibitor used to treat BRAF V600-mutant metastatic melanoma." (PMID 38183141, 2024). "The number of metastatic sites and baseline serum LDH were prognostic for disease progression and mortality in patients with BRAF V600 mutant metastatic melanoma treated with BRAF + MEK inhibitors." (PMID 39272837, 2024). "The recommended dose of encorafenib, 450 mg administered once daily (QD) in combination with binimetinib, 45 mg administered twice daily (BID), as indicated for patients with BRAF V600 metastatic melanoma, was used in this study." (PMID 38878209, 2024). "Prior to 2021, no prospective data were available to inform selection of first-line therapy for BRAF-mutant metastatic melanoma." (PMID 38167503, 2024). "The aim of our retrospective study was to determine the prognostic performance of clinicopathological factors and blood biomarkers in patients with unresectable metastatic melanoma treated with BRAF and MEK inhibitors." (PMID 39272837, 2024). "This study was designed to evaluate survival outcomes for sequential treatment with immunotherapy and targeted therapy in patients with BRAF-mutant metastatic melanoma." (PMID 37404764, 2023). "BRAF (vemurafenib, dabrafenib and encorafenib) and MEK (trametinib, cobimetinib and binimetinib) inhibitors have proven to improve survival in BRAF-mutant unresectable or metastatic melanoma, although half of the patients develop resistance within a year." (PMID 36766760, 2023). "Vemurafenib was first approved in April 2012 for the treatment of unresectable Stage IIIc or Stage IV metastatic melanoma positive for BRAF V600–mutant kinase activity." (PMID 37124503, 2023). "Vemurafenib, a BRAF inhibitor, has shown promise in the treatment of patients with metastatic melanoma, non‐small cell lung cancer, papillary thyroid carcinoma, hairy cell leukemia, and Langerhans cell histiocytosis." (PMID 37212518, 2023). "This led to improved survival for the BRAF defined biomarker- positive subgroup in metastatic melanoma." (PMID 37217528, 2023). "The BRAF inhibitor vemurafenib improves survival among patients with metastatic melanoma, hairy-cell leukemia and intracranial neoplasms with BRAF gene mutations." (PMID 36855200, 2023). "BRAF inhibitors (iBRAF) have revolutionized the treatment of BRAF V600E metastatic melanoma, but so far, results in CRC patients are disappointing due to resistance." (PMID 37629011, 2023). "On some occasions, it is also the only treatment available; this is the case of BRAF wild-type metastatic melanoma, where immunotherapy is the only therapeutic option." (PMID 36986683, 2023).
metastatic melanoma (continued). "Since the BRIM-3 trial with Vemurafenib and the BREAK-3 trial with Dabrafenib, BRAF inhibitors have shown greater benefit in improving outcomes for BRAF-mutant unresectable or metastatic melanoma patients compared to chemotherapy with dacarbazine." (PMID 37568570, 2023). "Notwithstanding, our study presented new and relevant data concerning the benefit of adding a palliative treatment with TT rechallenge for BRAF-mutant metastatic melanoma patients." (PMID 37568570, 2023). "Despite the encouraging results obtained with PLX4032, most BRAF-mutant metastatic melanoma patients become drug-resistant after 6/7 months of therapy, promoting cancer relapse." (PMID 37534247, 2023). "A recent multicenter, double-blind phase III trial (STARBOARD) of 624 patients with BRAF V600E/K metastatic melanoma compared the efficacy of triple therapy (encorafenib, binimetinib, and pembrolizumab) versus placebo plus PD-1 monotherapy (pembrolizumab)." (PMID 37569757, 2023). "The FDA also approved combination therapies including ipilimumab and nivolumab for BRAF V600 unresectable or metastatic melanoma and renal cell carcinoma." (PMID 36765809, 2023). "For example, a number of selective BRAF inhibitors (e.g., vemurafenib and dabrafenib) are available for patients with metastatic melanoma." (PMID 37240443, 2023). "For example, in non-small cell lung carcinoma (NSCLC), kinase activity profiling of tumor tissue has successfully differentiated short- from long-term survivors, and BRAF V600E from WT BRAF metastatic melanoma." (PMID 37760447, 2023). "The first patient (female, 55 years) had metastatic melanoma and multiple brain metastases for four years with ongoing partial tumor response during systemic treatment met BRAF/MEK-inhibitors." (PMID 38066225, 2023). "Seventeen percent of patients with metastatic melanomas received targeted therapy; in recent years, BRAF/MEK inhibitors have shown survival benefits in BRAF-mutated disease." (PMID 36831362, 2023). "Of the 62 metastatic melanoma patients (diagnosed between 2017 and 2018) with charts available for BRAF testing abstraction, 55 (88.7%) were tested for a BRAF mutation." (PMID 37185430, 2023). "TERT promoter mutations have been discussed as potential prognostic factors in metastatic melanoma and as potentially predictive most recently under BRAF/MEK and anti-CTLA4 therapy." (PMID 37418389, 2023). "BRAFV600E is prevalent in metastatic melanoma and novel strategies for BRAF and MEK inhibition are continuously developed and trialed to deliver long-term clinical response in patients." (PMID 37920169, 2023). "Four MEK inhibitors, trametinib, cobimetinib, binimetinib and selumetinib have been approved by FDA for the treatment of unresectable or metastatic melanoma alone or in combination with BRAF inhibitors." (PMID 38239196, 2023). "The PFS curves showed separation after 7 months of treatment, suggesting that addition of atezolizumab prolongs treatment benefit in BRAF-mutant metastatic melanoma." (PMID 37543586, 2023). "Kolenda and colleagues analyzed the association between plasma levels of lncRNAs and response to vemurafenib in BRAF-mutant metastatic melanoma patients." (PMID 37627054, 2023). "Our attention was drawn to the kinase RIPK4; it has structural similarity to the BRAF protein and is highly expressed in some primary and metastatic melanoma specimens and cell lines." (PMID 36765875, 2023). "Overall, our case demonstrates the importance and potential of the safety for treating hyperbilirubinemia and hypertransaminasemia in patients with metastatic melanoma with BRAF mutant." (PMID 36865793, 2023). "In this section, our perspective is focused on 7c (Vemurafenib, PLX4032), an ATP-competitive RAF inhibitor containing azaindole scaffold, which was approved by the US FDA in 2011 for the treatment of patients with BRAF-V600E metastatic melanoma." (PMID 36770611, 2023).
metastatic melanoma (continued). "We selected trametinib, an FDA-approved MEK inhibitor used to treat BRAF (V600E) mutant metastatic melanoma." (PMID 37500626, 2023). "Among the 55 metastatic melanoma patients who were tested, 23 (41.8%) were BRAF-mutant and 32 (58.2%) were BRAF-wildtype." (PMID 37185430, 2023). "In metastatic melanomas carrying BRAF, the combination of BRAFi with MEK inhibitor and immunotherapy represents a further step forward and a pilot clinical study suggests its clinical efficacy." (PMID 37183363, 2023). "Inhibitors of BRAF downstream MAPK and/or MEK are more effective than chemotherapy in the treatment of BRAFV600E-mutated metastatic melanoma." (PMID 36983983, 2023). "A two-patient case series published in 2015 reported the clinical activity of an MEK inhibitor (trametinib) in pre-treated metastatic melanoma patients with BRAF fusions." (PMID 37370834, 2023). "The majority of patients diagnosed with metastatic melanoma from 2017–2018 were tested for BRAF status and almost half of the patients with BRAF testing had a mutant BRAF test result (41.8%), which is consistent with estimates from large American studies." (PMID 37185430, 2023). "The clinical management of metastatic melanoma has been revolutionized by the introduction of BRAF and MEK inhibitors." (PMID 37790750, 2023). "Although performed in a limited number of patients, the study showed a fluctuating trend in CTCs levels in 4 of 5 patients with grade IV metastatic melanoma treated with BRAF and MEK inhibitors." (PMID 36835424, 2023). "A significant development in the current management of metastatic melanoma is the identification of BRAF V600E as a therapeutic target." (PMID 37745303, 2023). "In a retrospective trial, 79 patients with BRAF-mutant metastatic melanoma were treated with ≥ 1 line of immunotherapy followed by subsequent BRAFi/MEKi." (PMID 36995534, 2023). "The first reports documented in HCL patients treated with vemurafenib, a BRAF inhibitor approved for first-line treatment of unresectable or metastatic melanoma, been published in 2012." (PMID 38025907, 2023). "The 5-year survival rate of metastatic melanoma is 31–34% with targeted combined BRAF–MEK inhibitor therapy, 42–43% with anti-PD1 inhibitor therapy, and 46–57% with combined anti-CTLA-4 and anti-PD-1 therapy." (PMID 38202181, 2023). "Over the past decade, the treatment of metastatic melanoma has improved significantly due to the development of innovative therapies, such as drugs that target the BRAF/MAPK kinase pathway and the PD-1 pathway." (PMID 37111314, 2023). "Following the positive results obtained in BRAF V600E mutant patients with metastatic melanoma, the role of anti-BRAF drugs was investigated in other tumour types harbouring the same mutation." (PMID 36230797, 2022). "For instance, BRAF V600E, while a good predictor for metastatic melanoma, is a poor predictor of response in metastatic colorectal cancer." (PMID 36428696, 2022). "Previously, in two phase III trials, it was proven that a combination therapy with dabrafenib and trametinib improves PFS compared with dabrafenib alone (NCT01597908) or with vemurafenib alone (NCT01597908) in patients with BRAF mutant metastatic melanoma." (PMID 36358795, 2022). "Metastatic melanoma is one of the most aggressive tumor types, with frequent mutations mostly affecting components of the MAPK pathway, such as kinase BRAF." (PMID 36613518, 2022). "In 2013, the FDA approved trametinib for the treatment of BRAF V600E mutant metastatic melanoma, and in 2014 the FDA approved its use in combination with dabrafenib." (PMID 36699049, 2022). "BRAF testing is offered by the industry for metastatic melanoma and is available in several hospitals and clinics." (PMID 36589179, 2022). "In particular, it has been demonstrated that first-line BRAF/MEK-inhibitor (BRAF/MEKi) therapy evoked complete responses (CR) in 11–19% of BRAF-mutant metastatic melanoma patients with a median PFS between 11.1–14.9 months." (PMID 35565212, 2022).